IL10 (interleukin 10)
Diseases named in the same sentence as IL10 in open-access papers (continued):
Sharing a sentence is not in itself a finding about the gene and the disease.
COVID-19 (continued). "In severe cases of COVID-19, markers such as IL-10 and IFN-γ were elevated, and there was a notable increase in DNA damage indicators, suggesting that the prolonged inflammatory response in severe COVID-19 can contribute to genotoxic stress, which is a known precursor to carcinogenesis." (PMID 39350850, 2024). "A distinct immune response is noted between COVID-19 and MIS-C, characterized by a persistent elevation in pro-inflammatory cytokines such as IL-1β, IL-2, IL-6, IFN-α, IL-10, IL-17, granulocyte-macrophage colony-stimulating factor (GM-CSF), and high-mobility group box 1 (HMGB1) among MIS-C patients." (PMID 39931580, 2024). "At 9–12 weeks after disease onset, participants who had initially severe COVID-19 tended to have significantly higher levels of IP10 and sCD163 and lower levels of IL10, IL6, TNFα, IL17 and IL13 compared to those with mild or moderate disease, when adjusting for other covariates." (PMID 39008486, 2024). "Independent of initial disease severity, having received dexamethasone during acute COVID-19 was associated with higher levels of IL6, IL10, sCD14 and CRP compared to those who did not receive dexamethasone, in multivariable analyses." (PMID 39008486, 2024). "Additionally, IL-2Rα, IL-5, IL-10, HGF, and IP-10 were correlated with SOFA scores in patients with severe-to-mild COVID-19 at different disease stages." (PMID 38710800, 2024). "It has been found that adult COVID-19 patients in the intensive care unit (ICU) exhibit a significantly higher plasma level of IL-10 compared to those not in the ICU." (PMID 38355623, 2024). "Higher levels of IL-10 were seen in COVID-19 patients who did not develop long-term sequelae post infection compared to those who did." (PMID 39595087, 2024). "The pro-inflammatory cytokines that signal via the JAK-STAT signalling pathway include IL-2, IL-6, IL-8 and TNF-α, all of which are elevated in severe COVID-19, as well as antiviral or anti-inflammatory cytokines such as IFN-γ and IL10, which are also elevated in severe COVID-19." (PMID 39051370, 2024). "IL-10 is known to downregulate the inflammatory response, including the production of IL-6 and TNF-α, which are involved in the development of cytokine storms in severe COVID-19 cases." (PMID 39493183, 2024). "Previous studies have explored the correlation between serum levels of pro-inflammatory (IL-2, IFN-γ, TNF-α) or anti-inflammatory cytokines (IL-4 and IL-10) with clinical or negative outcomes in individuals with COVID-19." (PMID 38601541, 2024). "The immune inflammation factors, such as IL-6, IL-8, IL-10, CD8+ cell and NK cell, could serve as excellent biomarkers for monitoring or predicting COVID-19 progression therapeutic to COVID-19 patients." (PMID 38173531, 2024). "Hence, T-cell counts in COVID-19 were subsequently shown to be negatively correlated with IL-6, TNF-α and IL-10 blood levels, particularly in the elderly." (PMID 39896810, 2024). "Severe adult COVID-19 and MIS-C are characterized by excessive inflammation, including elevated inflammatory cytokines and chemokines such as tumor necrosis factor alpha (TNF-α), interleukin (IL) 6, IL-10, and IL-1β." (PMID 39494457, 2024). "The role of serological components in causing cardiovascular damage in COVID-19 is further corroborated by a significant negative correlation of IL-6, TNF-α, IL-1β, IL-10, and CRP levels with cardiomyocyte viability." (PMID 38041432, 2024). "First, we identified six cytokines and chemokines, including HGF (significant difference in cohort 1 and cohort 4) and IL-10, IP-10, SCGF-β, IL-16, and IL-18 (significant difference in cohort 3 and cohort 4), that consistently showed variations in COVID-19 in different cohorts." (PMID 38710800, 2024). "Especially with respect to TNFα and IL-10, it was evident their concentrations were similar in both the COVID-19 patient groups with no cardiovascular co-morbidities and those with cardiovascular co-morbidities without statin use." (PMID 39518552, 2024).
COVID-19 (continued). "Moreover, IL-10, IL6 and TNF-alpha, also biomarkers of COVID-19 severity, were exclusively upregulated in the placebo group at the protein level in serum." (PMID 38649734, 2024). "U tu su svrhu korišteni Komparativna toksikogenomska baza podataka (CTD), GeneMANIA i ToppGene Suite portal te je identificirana skupina od pet zajedničkih gena (IL1B, CXCL8, IL6, IL10, TNF) za šest metala i COVID-19, koji svi kodiraju proinflamatorne i antiinflamatorne citokine." (PMID 38963144, 2024). "TNFα but not IL-6 or IL-10 levels were increased in mild COVID-19 patients, compared to healthy controls." (PMID 36509969, 2023). "COVID-19 is characterized by increased interferon-γ (IFN-γ) and IL-1β, IL-4, and IL-10 production." (PMID 38131979, 2023). "While the levels of cytokines in lung in COVID-19 patients have not been analyzed, the plasma levels of IL-6, TNF-α, and IL-10 were highly increased in severe COVID-19 patients with comparable levels to non-COVID-19 patients." (PMID 37724101, 2023). "Results showed that IL-10 alone or in combination with IL23 and TNF-α are strongly linked with non-survivors in COVID-19 patients." (PMID 37283736, 2023). "Moreover, p62 modulation by NSP5 and ORF3a in vitro was involved in the regulation of TNF, IL-1, IL-6, IL-10, and IL-33 mRNA expression in THP-1 monocytic cell line, indicating a proinflammatory role of this autophagy receptor in COVID-19." (PMID 37174682, 2023). "Our results revealed an increase in the level of IL-35+IL-10+ producing CD138+CD1d+ Bregs (IL-35+IL-10+ Bregs) in the blood of severe patients compared to non-hospitalized patients with COVID-19 (30% increase in the frequency of IL-35+IL-10+ Bregs, P = 0.003)." (PMID 37833265, 2023). "Several proinflammatory cytokines such as tumor necrosis factor-alpha (TNF-α), interleukin (IL)-6, IL-2, IL-7, and IL-10 are involved in the development of cytokine release syndrome (CRS), which then contributes to the high morbidity and mortality of COVID-19 including ARDS." (PMID 37047115, 2023). "Our current study concluded that, miR-20a, IL-10 and TLR4 are potential biomarkers for severity of COVID-19 disease and also blockade of IL-10 and TLR4 may constitute a novel therapy for COVID-19 patients." (PMID 36864077, 2023). "COVID-19-depleted carbohydrate metabolites and neurotransmitters had a positive correlation with reduced levels of cytokines (e.g., CCL22, IL-12 and IL-13) while negatively correlated with increased levels of inflammatory cytokines (e.g., IL-6 and IL-10)." (PMID 37205106, 2023). "Several studies showed that high IL-10 expression levels predict negative outcomes in patients with COVID-19, and this appears to be a characteristic mark of hyper-inflammation during severe SARS-CoV-2 infection." (PMID 37237997, 2023). "Plasma levels of IL-2, IL-7, IL-10, granulocytic stimulator, IP-10, human monocyte chemotactic protein 1, and human macrophage inflammatory protein 1α in ICU patients with COVID-19 are higher than those in mild patients, indicating strong correlation between cytokine storm and disease severity." (PMID 38156008, 2023). "Simultaneously assayed anti-spike T cells producing IL-4 or IL-10 were minimal for vaccinees, whereas several COVID-19-recovered persons exhibited IL-4 but not IL-10 responses of unclear significance." (PMID 36860850, 2023). "We concluded that, miR-20a, is a potential biomarker of COVID-19 severity and blockade of IL-10 and TLR4 may constitute a novel therapy for COVID-19 patients." (PMID 36864077, 2023). "A systematic review of 52 articles involving 6320 COVID-19-positive patients revealed that elevated levels of neutrophil count, WBC, prolonged PT, ESR, D-dimer, fibrinogen, procalcitonin, IL-6, and IL-10 can more significantly progress to a more serious form of COVID-19 infection." (PMID 37235308, 2023).
COVID-19 (continued). "The immune response in COVID-19, which may result in ARDS, involves the unbalanced secretion of various inflammatory cytokines and chemokines, including TNF-α, IL-1β, IFN-γ, IL-6, IL-10, IL–1RA, IP–10, MCP–1, and IL-8 (CXCL8)." (PMID 37600829, 2023). "However, levels of IL-10 and TGF-β cytokines were higher in COVID-19 patients than in controls and were much higher in severe cases than moderate ones." (PMID 38139439, 2023). "Among them, several of the classical inflammatory markers, e.g., IL6, IL8, IL10, IL12B, TNF, and IFNγ had substantially higher levels in sepsis compared to COVID-19, leading to the conclusion that the inflammatory response is more pronounced in sepsis regardless of etiology or focus of infection." (PMID 36829233, 2023). "A protein–protein interaction network analysis identifies sIL2R, IL6, IP-10, IL-10 and MIG as the network path with the highest inflammation in MIS-C relative to COVID-19, indicating that there are two pathways mediated by NFkB and IFN-Υ leading to elevated IP-10 and MIG." (PMID 37685502, 2023). "Additionally, COVID-19 patients had increases in inflammatory biomarkers such as IP10 (median 429.1 vs 22.4pg/mL), IL-10 (median 9.3 vs. 1.3pg/mL), and RAGE (median 2476 vs. 686pg/mL), when compared to disease controls." (PMID 36999030, 2023). "In PBMC generated from COVID-19 patients receiving ICU care, recent research looked at Tregs and discovered a sharp fall in the proportion of Tregs along with lower production of FoxP3 and inhibitory cytokines such as IL-10 and TGF-beta." (PMID 36992283, 2023). "Patterns of cytokine alterations in AP and COVID-19 were shown to be remarkably similar in a recent meta-analysis, with tumor necrosis factor-alpha (TNF-α), interleukin (IL)-6, IL-8, and IL-10 concentrations significantly higher in more severe forms than non-severe forms of the two diseases." (PMID 36834656, 2023). "In the PCA, while the non-KTRs with COVID-19 were differentiated from their controls in their IL-10, IFN-α, and TNF-α, this pattern was marked in the NGAL, sVCAM-1, and IL-8 of the KTRs." (PMID 38005844, 2023). "Interestingly, IL-10, CXCL9, CCL3, and VEGF levels were significantly higher in the COVID-19 group than those in the HC group." (PMID 37422499, 2023). "The TNFα/IL-10 radio, an indication of the balance between key pro- to anti-inflammatory levels, was also reduced to a similar level in severe, critical COVID-19, and non-COVID-19 critical patients." (PMID 36509969, 2023). "Analysis of regulatory T cells (Tregs) revealed decrement in percentage of CD4+ FoxP3+ T cells as well as in percentage of CD4+ IL-10 producing T cells (data not shown) in terminal stage of COVID-19." (PMID 37057213, 2023). "Pathway analysis identified several immunity-related genes that may link ADHD to COVID-19, including CRP, OXT, IL6, PON1, AR, TNFSF12, and IL10." (PMID 38066446, 2023). "Altogether these data highlight that the presence of a well-known inflammatory microenvironment in severe COVID-19 patients might be reflected in more activated ILC2 producing high concentrations of both IL-5 and IL-10." (PMID 37207201, 2023). "In addition to elevated IL-10 levels, TNF-α and IL-23 were also increased in serum of COVID-19 patients and correlated positively with CRP levels." (PMID 37283736, 2023). "The levels of Nrf2, HO-1, NFκB, and IL-6 were higher in the granulocytes of COVID-19 patients who died within a week, while the activity of cytoplasmic Cu,Zn-SOD and mitochondrial Mn-SOD and IL-2/IL-10 were lower in comparison to the levels observed in survivors." (PMID 37686388, 2023). "These include interleukin-1 (IL-1), IL-6, IL-18, IL-10, interferon gamma (IFN-γ) and tumor necrosis factor-alpha (TNF-α) secreted by T helper type 1 (TH1) and other cells during the inflammatory process of COVID-19." (PMID 37447302, 2023).
COVID-19 (continued). "Correspondingly, circulating levels of pro-inflammatory cytokines IL-6, TNF and IFN-γ, and of anti-inflammatory IL-10, were altered with respect to reference values but similar in COVID-19 and No COVID-19 patients." (PMID 37408073, 2023). "The mediators CCL3, CCL4, CCL2, CCL5, IL-12, IL-15, IL-1Ra, and PDGF were higher in healthy volunteers, while the mediators CCL11, CXCL10, IL-1b, IL-6, TNF-a, IFN-g, IL-17, IL-9, IL-10, IL-13, FGF-basic, G-CSF, GM-CSF, IL-7, and IL-2 were increased in COVID-19 positive patients." (PMID 37903875, 2023). "Additional studies have also revealed that patients with severe COVID-19 have a significantly elevated cytokine profile of IL-2, IL-6, IL-7, IL-10, IP-10, MCP-1, TNF-α, macrophage inflammatory protein 1 alpha, and granulocyte-CSF compared to patients with mild to moderate COVID-19." (PMID 37457959, 2023). "The positive association between HERV-W with IL-6 expression and the negative association with IL-10 are in line with the immunopathogenic role of the ENV HERV-W protein as described in MS and recently in COVID-19." (PMID 37894766, 2023). "We selected the IL-10 and TGF-β cytokines since previous studies revealed that anti-inflammatory molecules such as IL-10 and TGF-β can be predictive indicators of medical severity, fibrosis of the lungs, and death in COVID-19 patients." (PMID 38139439, 2023). "Lu, 2021 related that cytokine storm is similar to COVID-19 and SARS-CoV patients, but in severely ill COVID-19 patients, IL-10 is incredibly elevated, which suggests that IL-10 could be a putative biomarker." (PMID 36992353, 2023). "Consequently, patients with severe COVID-19 have considerably higher blood levels of IL-2, IL-6, TNF-α, IL-1, IL-10, IFN-γ, IL-8/CXCL8, and CXCL10/IP-10 during the cytokine storm, potentially because of NF-κB via selective activation." (PMID 36851766, 2023). "Another study found a comparable rise in the Th17/Treg ratio in the PBMC of COVID-19 patients, which was associated with a negative outcome and lower levels of TGF-beta and IL-10, cytokines that are important for Tregs." (PMID 36992283, 2023). "Additionally, in COVID-19 patients, serum levels of IL-6, TNF-α, IL-8, and IL-10 were negatively correlated with lymphocyte counts." (PMID 37654571, 2023). "The aim of this study was to investigate the relationship between the serum levels of a panel of pro-inflammatory cytokines consisting of IL-6, IL-8, IL-10, IL-12, TNF-α, IFN-γ and disease severity, need for oxygen therapy, ICU transfer and fatal outcome in patients with confirmed COVID-19." (PMID 37969879, 2023). "The strength of our study lies in the comprehensive dynamics of the pro-inflammatory (mainly IL-1β, IL-6, IL-8, TNF-α) and anti-inflammatory (IL-10) cytokines over time and their comparison with non-severe COVID-19 cases as supporting evidence." (PMID 37384050, 2023). "Studies suggest that serological levels of IL-10 are elevated in severe cases of COVID-19 through a negative feedback mechanism suggesting both pro-inflammatory activity and anti-inflammatory response." (PMID 37239991, 2023). "In a retrospective study, LMW heparin was shown selectively to reduce plasma IL-6 concentrations, but not concentrations of IL-2, TNF-α, IL-4, IL-10 or IFN-γ in patients with COVID-19." (PMID 37111341, 2023). "Finally, ROC curve results uncovered that IL-10, IL-23 and TNF-α were excellent predictors for prognosing COVID-19." (PMID 37283736, 2023). "Both IL-10 and PDGF-A were increased in the dialysate of COVID-19 patients." (PMID 37674148, 2023). "Regarding Bregs, compared to the milder, non-hospitalized cases, the proportion of IL-35+ and IL-10+ Bregs was elevated in the blood of severe COVID-19 patients, and to a higher extent in those with auto-Abs to type I IFNs." (PMID 37833265, 2023).
COVID-19 (continued). "Many secretomes from both asymptomatic groups, Kisumu and Elgeyo Marakwet, clustered with high IL-10 levels, which was not seen for the secretomes from symptomatic COVID-19 convalescents from Singapore." (PMID 37219944, 2023). "Similarly, elevated levels of IL-6, IL-10, IL-2 and IFN-γ were found in patients with severe COVID-19 due to respiratory failure." (PMID 37917760, 2023). "The anti-inflammatory cytokine IL-10 was downregulated in pregnant and non-pregnant COVID-19 cases, whereas TGFβ1 was upregulated in both groups." (PMID 37016066, 2023). "A unique feature of the cytokine storm in COVID-19 is the dramatic elevation of interleukin 10 (IL-10), which is regarded as a negative feedback mechanism to suppress inflammation." (PMID 37853311, 2023). "Previous studies found increased the Th2 cytokine profile (i.e., IL-4 and IL-15) and IL-10 in the blood of recovered mild COVID-19 patients without sequelae." (PMID 37753077, 2023). "Cytokine detection: Comparing cytokine levels quantification in laboratory controls and patients in the 4/6-day collection after study admission, it was seen that non-severe COVID-19 cases showed an increase in IL1β, IL-6, IL-10 and TNF." (PMID 37515295, 2023). "In this study, the circulating cytokines quantification showed that patients with COVID-19 have increased levels of IL-6 and IL-10 in the collections 4–6 days regardless of severity." (PMID 37515295, 2023). "Some authors have described a relation between IL-10 systemic levels and COVID-19, particularly pain related, showing a strong negative correlation between IL-10 systemic levels and pain intensity." (PMID 35455024, 2022). "This explains the negative correlations observed between IL-10 and basophils in COVID-19 active cases." (PMID 36094915, 2022). "A recent comprehensive meta-analysis reported the enhanced level of Interferon-γ (IFN-γ), TNF-α, IL-10, IL-8, IL-6, IL-4, IL-2R and IL-2, whereas no significant increase in IL-17 and IL-1β level among severe COVID-19 patients." (PMID 36298704, 2022). "Critically ill patients who survived COVID-19 and Long-COVID patients showed elevated levels of the anti-inflammatory cytokine IL10, which was independent of N-protein levels." (PMID 36293090, 2022). "Our meta-analysis results show that IL-10 is increased in severe cases and non-survivors relative to mild or survivor COVID-19 cases." (PMID 35572964, 2022). "The expression of the immune system-related SNPs in COVID-19 (the IFNA, IL10 and HLA genes), however, could be affected by the levels of VD." (PMID 36430729, 2022). "The death-to-live ratio of COVID-19 patients was 457:43 indicating that the patients having elevated levels of both CKMB, D-dimer, CK and IL-1, IL-6, IL-10 and D-dimer, Troponin, CK and IL-1, IL-10 had high fatality rate (73% and 12% respectively)." (PMID 36298704, 2022). "Moreover, COVID-19 patients who were admitted had a substantial accumulation of inflammatory cytokines, including TNF-а, IL-6, IL-2, and IL-10, especially in severe COVID-19." (PMID 35573725, 2022). "In the same way, IL-10 directly expands cytotoxic effector CD8+ T-cells in human studies, provoking a hyperactivation of adaptive immunity in COVID-19 patients, which might contribute to exacerbating disease severity." (PMID 36497139, 2022). "This post-COVID-19 inflammatory syndrome was originally diagnosed as Kawasaki disease; however, patients with MIS-C display more pronounced lymphopenia, thrombocytopenia, anemia, and elevated serum IFN-γ, IL-1β, IL-6, IL-10, and IL-17 levels." (PMID 35464491, 2022). "Indeed, an increase in cytokines such as TNF-α, MCP-1, IL-6, IL-1β, and IL-10 was shown in the rat ARDS model induced by LPS administration, which corresponds to the cytokine profile of patients with a severe form of COVID-19." (PMID 36290634, 2022).